DICER1 (dicer 1, ribonuclease III)
Diseases named in the same sentence as DICER1 in open-access papers (continued):
Sharing a sentence is not in itself a finding about the gene and the disease.
uterine corpus endometrial carcinoma (1 paper, 2019). A endometrial carcinoma (disease) that involves the body of uterus. "Of these 16 LP DICER1‐carriers, we found one patient with a uterine corpus endometrial carcinoma who harbored a p.Ala1578Thr germline DICER1 variant and a somatic DICER1 hotspot variant (p.Asp1709Asn)." (PMID 30672147, 2019). "In addition, another subject with a uterine corpus endometrial carcinoma harbored two germline P DICER1 variants: a splice‐donor c.4206+1G>C and an RNase IIIb missense (hotspot) p.Asp1810Asn." (PMID 30672147, 2019). "Our observation of germline P/LP DICER1 variation in 0.6% (3/524) of TCGA uterine corpus endometrial carcinoma merits additional investigation." (PMID 30672147, 2019). "The observation of germline DICER1 variation with uterine corpus endometrial carcinoma merits additional investigation." (PMID 30672147, 2019). "In summary, 0.6% (3/524) of women in TCGA with a uterine corpus endometrial carcinoma harbored germline P/LP DICER1 variation." (PMID 30672147, 2019).
visceral leishmaniasis (1 paper, 2017). A severe form of leishmaniasis characterized by irregular bouts of fever, substantial weight loss, swelling of the spleen and liver, and anemia (which may be serious). "Recently, it has been documented that low serum cholesterol in mice with visceral leishmaniasis is associated with downregulation of miR‐122 through the degradation of its processor, Dicer1, by the metalloprotease gp63, which inhibits cholesterol biosynthesis in infected mouse liver." (PMID 28349644, 2017).
Wilms renal tumors (1 paper, 2025). "Among the adherent cultures there were five cultures that later turned out to be derived from non-Wilms renal tumors according to reference pathology (2 CMN, 2 CCSK, 1 CN with the typical EGFR-ITD, BCOR-ITD and DICER1 mutations)." (PMID 39740515, 2025).
tumor (276 papers, 2007 to 2026). "Current recommendations for tumor surveillance in individuals carrying pathogenic DICER1 variants entail regular clinical and imaging assessments, such as chest radiography or computed tomography (CT) and ultrasound of the thyroid, abdomen, and pelvis." (PMID 41528496, 2026). "Our prior work established that endothelial loss of Dicer1, a key enzyme in microRNA (miRNA) processing, drives AS formation in mice, indicating a tumor suppressive role for miRNAs in tumorigenesis." (PMID 41748289, 2026). "Tumor entities associated with pathogenic DICER1 variants typically manifest at a young age (< 40 years)." (PMID 41528496, 2026). "DICER1 tumor predisposition (OMIM 606241) is caused by pathogenic variants (PVs) in the DICER1 gene." (PMID 40634537, 2025). "DICER1 is a tumour suppressor gene that encodes a ribonuclease involved in the processing of small RNAs, including those that play a role in RNA interference." (PMID 40389436, 2025). "Management for patients with a DICER1 mutation entails routine surveillance for tumor development including periodic thyroid ultrasounds, renal ultrasounds, tumor markers and chest x-rays, and genetic counseling." (PMID 40918549, 2025). "Genetic analyses revealed variants in the DICER1 gene in the tumor tissue (c.5125G>A) and peripheral blood (c.4458dupA)." (PMID 40861331, 2025). "These tumours, characterised by somatic DICER1 hotspot mutations, differ from teratomas or carcinosarcomas and often occur in older individuals without a familial cancer history." (PMID 41104964, 2025). "DICER1 is generally regarded as either a tumor suppressor gene when loss-of-function mutations occur or as an oncogene when gain-of-function mutations are present." (PMID 39860595, 2025). "Here, we report a case of this rare tumor in a 2-year-old girl with a family history of cancer that was found to have DICER1 variants." (PMID 40861331, 2025). "We and others have previously reported that mice with an inactivating mutation in the miRNA-processing enzyme, Dicer1, specifically in myeloid cells exhibit delayed tumor growth in multiple cancer models." (PMID 40475851, 2025). "The presence of another DICER1-associated neoplasm should guide the clinician and pathologist to suspect a germline mutation." (PMID 41104964, 2025). "At a somatic level, the nodule displayed a single hotspot somatic mutation of DICER1 p.(Asp1810 Tyr), shared by both the differentiated component of the tumor and the 8-mm high-grade area." (PMID 40448797, 2025). "The frontal and frontoparietal lobes were the most common tumor locations, and the molecular profiling in all 10 cases revealed DICER1 mutation." (PMID 41522384, 2025). "When diagnosing some of these uncommon neoplasms, the pathologist should raise the possibility of a germline mutation, for example DICER1 in SLCT or SMARCA4 in SCCOHT and recommend genetic referral and germline testing." (PMID 40739655, 2025). "It is thought that by the ages of 10 and 50 years, approximately 5% and 19% of patients with a germline DICER1 pathogenic variant will develop a neoplasm, respectively, with females being at a significantly higher risk than men." (PMID 40076617, 2025). "This study reviewed existing research and examined data from a German pediatric tumor registry to explore how often DICER1 mutations appear in tumors like ETMR and intracranial sarcomas." (PMID 40361440, 2025). "Two aggressive tumour entities have also been linked to DICER1 mutations and are now recognised in the 2022 WHO classification." (PMID 41104964, 2025). "While our data identified an appreciable fraction of DICER1‐mutated tumours with oncocytic features, we acknowledge that these observations are based on a relatively small sample size and do not achieve formal statistical significance." (PMID 41104964, 2025).
tumor (continued). "The tumor also had a germline single base insertion in the DICER1 gene, which caused a frameshift and premature stop codon." (PMID 39857323, 2025). "Though Dicer1 downregulation has been linked to tumor progression, complete loss of Dicer1 function is extremely rare." (PMID 41002430, 2025). "Regarding paediatric tumours, DICER1 mutations have been highly frequent in paediatric low-risk follicular-patterned tumours, IEFVPTC, and FTC." (PMID 41104964, 2025). "The tumor susceptibility in patients with DICER1-related diseases is inherited in an autosomal dominant manner." (PMID 40226310, 2025). "DICER1 variants were initially implicated in the development of pleuropulmonary blastoma, but numerous other associated tumours and clinical features have been described since this discovery." (PMID 40361475, 2025). "This will aid in the general knowledge of DICER1 syndrome to better predict risk of tumor formation in individual patients and to hopefully find a targeted therapy for these individuals." (PMID 40940982, 2025). "Studies suggest that Dicer1 functions as a haploinsufficient tumor suppressor gene: partial loss promotes tumorigenesis, while complete loss prevents it." (PMID 39409030, 2024). "In general, DICER 1-associated neoplasms should guide the clinician and pathologist to suspect either germline or somatic DICER1 mutations." (PMID 38254836, 2024). "Next generation sequencing identified somatic hotspot mutations in DICER1 in five of six tumors and whole exome sequencing identified one tumor with a germline pathogenic DICER1 variant and one with loss of heterozygosity for DICER1." (PMID 38254836, 2024). "Prognostic determinants, such as age at diagnosis, tumor size and location, distant metastases, and molecular markers - including mutations in the DICER1 gene, an autosomal dominant tumor suppressor - have been associated with PPB." (PMID 39583508, 2024). "This two-hit theory seems to be also required in other miRNA biogenesis genes, like DROSHA and DICER1, in some specific types of tumor, where the hotspot mutation is always accompanied by another loss of function (LOF) mutation or LOH." (PMID 38607000, 2024). "Tumor samples exhibiting both high DICER1 and DROSHA expression were linked to improved median survival rates." (PMID 39596271, 2024). "In DICER1-related tumor predisposition, the germline variant is typically the loss of function, and the somatic second hit generally occurs in one of a handful of hotspot codons." (PMID 38084291, 2023). "Developmental delay and a syndromic phenotype combined with classical DICER1-associated tumours have been rarely reported and are described in association with a 14q32 deletion encompassing the DICER1 locus." (PMID 34331184, 2023). "Our study provides a combined approach to classify DICER1-associated neoplasms, which not only has diagnostic implications but will also facilitate future investigations into prognostication and therapeutic approaches for patients with such tumors." (PMID 36966138, 2023). "In this setting, thorough sampling of the tumor is essential, to look for well-differentiated tumor areas, as well as an integrated histomolecular approach (i.e., DICER1 and FOXL2 variant testing) to better classify these tumors." (PMID 38136408, 2023). "Surveillance recommendations aimed at early tumor detection exist for those with DICER1-related tumor predisposition due to germline variants in DICER1." (PMID 38084291, 2023). "Due to the characteristic signature of DICER1 somatic mutations, the DICER1 VCEP chose to use somatic tumor testing as supporting evidence (PP4)." (PMID 38084291, 2023). "Most DTPS-causing GPVs are nonsense or frameshifting, with tumor development requiring a second somatic missense hit that impairs the DICER1 RNase IIIb domain." (PMID 37333613, 2023). "Next-generation sequencing was performed on paired tumor-germline samples for both patients, revealing mutations in DICER1." (PMID 37835574, 2023).
tumor (continued). "Identifying a germline pathogenic DICER1 variant in an individual allows the clinicians to provide appropriate surveillance to prospectively screen for further DICER1-associated tumours and to offer genetic testing for all first-degree relatives." (PMID 37248399, 2023). "Most cases have a germline DICER1 heterozygous pathogenic variant, leading to an increased risk of developing tumours." (PMID 37626640, 2023). "With increasing awareness of their distinctive morphology and the use of modern genetic tools, DICER1-associated lesions and neoplasms (both benign and malignant) are becoming increasingly recognized in surgical pathology." (PMID 34282560, 2022). "The DICER1 protein immunostaining was extensively positive in the tumor cells, indicating the high possibility of DICER1 mutation." (PMID 36153506, 2022). "The presentation of a DICER1-associated neoplasm in the male reproductive tract contrasts at the moment with the apparent more common occurrence in females." (PMID 34599283, 2022). "This composite of histologic features is another example of the common morphologic motif of several other pulmonary and extrapulmonary DICER1-associated neoplasms." (PMID 34599283, 2022). "Aside from PPB, several other characteristic neoplasms have been reported in DICER1 mutation carriers, including cystic nephroma, rhabdomyosarcoma, multinodular goiter and thyroid carcinoma, which often develops in childhood." (PMID 35163487, 2022). "ES of DNA prepared from kidney and lung tumour tissue revealed that the germline heterozygous mutation c.4031C>T in DICER1 was more abundant in the tumour tissue, 87% and 90%, respectively." (PMID 33208384, 2022). "This morphologic association of cystic structures with a myxoid stroma and accompanying islands of cartilage follows the histologic motif of the other DICER1-associated neoplasms." (PMID 34599283, 2022). "These two cases again highlight the importance of the potential histologic clues to a DICER1-associated neoplasm." (PMID 34599283, 2022). "Several examples of primary CNS neoplasms have been reported with histologic features similar to other DICER1-associated neoplasms including PPB79,165,181–185." (PMID 34599283, 2022). "None of these children had a past or contemporaneous history of PPB or other DICER1–associated neoplasms." (PMID 34599283, 2022). "A recent case in a 22-year-old female with a DICER1 germline variant and two previous DICER1-associated neoplasms showed extensive capsular and vascular invasion and multiple foci of tumor and nodular hyperplasia in the resected thyroid." (PMID 34599283, 2022). "Different from most tumor suppressor genes, loss of one DICER1 allele is sufficient to induce tumorgenesis, while homozygous deletion is rare in DICER1-related diseases." (PMID 34322384, 2021). "This included 12 patients with confirmed germline DICER1 mutations (or 14q32 deletion in one case); six of them also had a somatic DICER1 mutation in the tumor." (PMID 33673661, 2021). "DICER1 is considered a haploinsufficient tumor suppressor, as loss of a single Dicer1 allele promotes tumorigenesis and reduces survival in mice." (PMID 34853298, 2021). "This neomorphic function leads to the tumor suppression to falter when the expression of wild-type DICER1 allele is impaired due to an LoF variant or a loss of heterozygosis (LOH) event." (PMID 33922805, 2021). "For example, mutations in or reduced expression of DROSHA and DICER1 in tumors associate with advanced tumor stage and poor clinical outcome in cancer patients." (PMID 34853298, 2021). "Alterations in DICER1 lead to dysregulation of miRNA production, which is associated with different tumour types." (PMID 34552563, 2021). "Ultimately, it is hoped that patient-specific (epi)genetic factors can be taken into account when estimating DICER1-associated tumor risks and developing (personalized) surveillance protocols." (PMID 34170462, 2021).
tumor (continued). "To summarize, we present the rare occurrence of an MV-FTC and further substantiate the association between this unusual tumor type and DICER1 hotspot mutations." (PMID 32712880, 2021). "It is notable that on manual review of the EHR, the term DICER1 did not appear in any of the records of the 25 participants with a pLOF DICER1 variant, even in the records of patients with a known DICER1-associated tumor or thyroid phenotype." (PMID 33630087, 2021). "For example, individuals with mosaicism for DICER1 pathogenic missense variants in the RNase IIIb domain present with more severe DICER1-associated phenotypes, including higher tumor burden, earlier age of onset and greater range of phenotypes." (PMID 34170462, 2021). "In this report, we describe an MV-FTC with a somatic DICER1 mutation occurring in a young female patient and detail the cytological and histological work-up of this rare tumor example." (PMID 32712880, 2021). "If indeed bi-allelic, the mutations strongly support an abolished tumor-suppressor function of DICER1 as an important genetic mechanism underlying the development of MV-FTCs." (PMID 32712880, 2021). "Malignant tumors were observed in 16% of participants with a DICER1 pLOF variant, which is comparable to the frequency of neoplasms in the largest phenotype-first DICER1 studies published to date." (PMID 33630087, 2021). "Individuals with 14q32 deletions that encompass the DICER1 locus are also associated with an increased risk for DICER1-related tumor development." (PMID 33495912, 2021). "Sequencing of paired tumor and normal tissue samples indicated a somatic nature of the detected DICER1 mutation." (PMID 32507920, 2020). "Based on segregation, confirmation and functional validation, we identified DICER1 as a candidate HL predisposing gene by showing significant down-regulation of tumor suppressor miRNAs in DICER1-mutated family members." (PMID 32211398, 2020). "Additional DICER1-associated neoplasms were diagnosed in one of the two children and a presumed intracranial metastasis in the other." (PMID 32507920, 2020). "PPB has been linked to the mutation of DICER1 as part of a predisposition syndrome for different types of tumours." (PMID 33028416, 2020). "Another surprising finding is that this cell line, as well as the primary tumor, carries a missense hotspot mutation of DICER1 in its RNase IIIb domain." (PMID 33052929, 2020). "DICER1 mutations are responsible for familial tumour susceptibility syndrome with an increased risk of tumours." (PMID 33028416, 2020). "Deleterious germline and somatic DICER1 variants have also been reported in various sporadically occurring neoplasms." (PMID 32714280, 2020). "recently published the first quantitative analysis of site-specific neoplasm risk, analyzing the standardized incidence ratios of 207 individuals carrying DICER1 variants, selected combining data from three large cohorts of patients." (PMID 33552988, 2020). "In most syndrome’s neoplasms a biallelic pathogenic variant in DICER1 has been detected: usually a germline loss-of-function pathogenic variant in one allele and a tumor-specific somatic hotspot variant in the second allele." (PMID 33552988, 2020). "Targeted next-generation sequencing (NGS) detected DICER1 mutation in the plasma samples and postoperative tumor tissues of both patients." (PMID 32629665, 2020). "TAp63 suppresses tumorigenesis and metastasis by direct binding to DICER, suggesting both genetic mutation and functional inactivation of DICER1 dictate global miRNA expression in tumor malignancy." (PMID 32138313, 2020). "The risk for most DICER1-associated neoplasms is highest in early childhood and decreases in adulthood." (PMID 33028416, 2020). "These analyses yield insights into tumor-specificity of DICER1 mutations and their consequences on miRNA and mRNA profiles." (PMID 31417090, 2019).